ENSG00000278237
Gene: Miscellaneous RNA gene on chromosome 5 (76,712,763 to 76,712,861, forward strand). Ensembl gene ENSG00000278237.
Gene Ontology:
Biological process: positive regulation of gene expression